CD34 (CD34 molecule)
Diseases named in the same sentence as CD34 in open-access papers (continued):
Sharing a sentence is not in itself a finding about the gene and the disease.
tumor (continued). "MVD labeled with CD34 was used to assess tumor angiogenesis in the same way." (PMID 33442403, 2021). "Therefore, the border of each group of tumors comprises stromal cells with an opposite expression to that of the tumor: αSMA+ stromal cells for CD34+ tumors and CD34+ stromal cells for αSMA tumors." (PMID 34298962, 2021). "Sabisz and Sklandanowski (2009) determined that about 1% of the nonsmall lung adenocarcinoma A549 cells treated with DNA damaging drugs escaped senescence and lead to regrowth of tumor cell population accompanied with an increase in cancer stem cell marker expression (CD34 and CD117)." (PMID 33524223, 2021). "Further bioinformatics analysis based on the TCGA database revealed that cluster analysis of tumor samples based on CD34/CD276 mRNA expression could well predict the survival status of patients." (PMID 34307389, 2021). "This corresponded to a 1.8 ± 0.2-log tumor cell depletion of the PBPC product while 93.5 ± 2% of CD34+ cells and 81.0 ± 4.4% of PBPCs were retained as indicated by relative center fraction recovery rates of 6.5 ± 2% and 19.0 ± 4.4% for CD34+ cells and PBPCs, respectively (n = 2, mean ± SD)." (PMID 34654486, 2021). "Univariate Cox proportional hazard analysis indicated that the presence of cells expressing CD3 (hazard ratio (HR): 0.5, p = 0.018), CD34 (HR: 0.53, p = 0.004), and ICOS (HR: 0.6, p = 0.047) in tumour compartments was associated with improved overall survival (OS)." (PMID 33261133, 2020). "Moreover, the expression level of CD34 in the endothelium of newly-formed blood vessels is higher than that in old blood vessels, suggesting that CD34 is involved in tumor neovascularization." (PMID 32962642, 2020). "In this study, we proposed radiomics features and the binary logistic regression model to identify the immunohistochemical typing of Ki-67, S-100, CD34 and vimentin, so as to achieve the image-indication of tumor progression, angiogenesis, proliferation or invasion." (PMID 31968004, 2020). "The tumor also contained numerous capillary channels positive for CD34 staining." (PMID 32235007, 2020). "Conversely, high expression of CD34 suggests increased tumor microangiogenesis." (PMID 32962642, 2020). "On IHC, tumour cells were positive for vimentin, cytokeratin and CD34." (PMID 33520482, 2020). "Partial preservation of CD34+ fibroblasts in the tumor stroma of ILC was confirmed." (PMID 32435886, 2020). "By immunohistochemistry, the tumor cells stained positively for S-100 (focal +), CD34 (strong +++), and Ki-67 (20%), and negatively for smooth muscle actin, pan-cytokeratin (CK), neurofilament (NF), pan-cytokeratin-L, GFAP, CD31, STAT6, ERG, myogenin, and MyoD1." (PMID 32590748, 2020). "Immunohistochemical staining revealed that the tumor cells were positive for CD34, CD99, and BCL2." (PMID 32638177, 2020). "Next, we investigated whether the CD34 status (CD34 high versus CD34 low) affects the propagation to the secondary tumour." (PMID 33123267, 2020). "The band-like tumor was strongly positive for synaptophysin and contained multiple ectatic blood vessels, which could be clearly depicted by CD34 immunohistochemistry." (PMID 32049624, 2020). "Moreover, the expression levels of CD31 and CD34 in tumor specimens from 314 HCC patients were also detected by IHC staining, to investigate the correlation between HOXA5 and MVD." (PMID 32373208, 2020). "The degree of intra-tumor angiogenesis in ccRCC might be quantified by measuring the microvessel density (MVD) by means of CD34 expression assessment." (PMID 32620162, 2020). "Moreover, CD34 demonstration is a reliable and consistent technique for gauging tumor vascularity, therefore it is critical to analyze markers including CD34 and α-SMA in early tumor biopsies to estimate the metastatic behavior." (PMID 33383808, 2020).
tumor (continued). "Additionally, these have been associated with the expression of tumor markers such as MB1, CD34, and CA 153 with a significant role in prognosis, progression, and discrimination between benign and malignant lesions." (PMID 33297469, 2020). "CD34 is a marker of microvascular density and angiogenesis, which is vital for tumor progression." (PMID 33168005, 2020). "We examined tumor related angiogenesis by using the tube formation assay and CD34 IHC staining." (PMID 33194674, 2020). "The release of VEGF promotes tumor neovascularization and expression of CD34." (PMID 32962642, 2020). "Additionally, CD34 staining was also positive in tumor nodules, indicating angiogenesis in the tumor tissue, which is a common feature in HCC." (PMID 32296582, 2020). "Neuronal cells were positive for synaptophysin and some tumor cells showing positivity for CD34." (PMID 32451719, 2020). "Abundant CD34‐positive tumor aggregates can be identified within adjacent neocortex." (PMID 32058680, 2020). "Univariate Cox proportional hazards indicated that the presence of cells expressing CD3 (hazard ratio (HR): 0.5, p = 0.018), CD34 (HR: 0.53, p = 0.004), and ICOS (HR: 0.6, p = 0.047) in tumour compartments were significantly associated with improved overall survival (OS)." (PMID 33261133, 2020). "CD34 is expressed in the small blood vessels of tumor tissues." (PMID 32962642, 2020). "CD34 is commonly used for evaluating neovascularity and tumor behavior." (PMID 32974148, 2020). "Interestingly, expression data from immune ROIs indicated that the presence of EpCAM and cytokeratin was associated with better patient OS, while the presence of CD34, CD3, and ICOS in tumour ROIs was associated with better patient OS." (PMID 33261133, 2020). "However, the growth transforming ability of EBV allows for the generation of autologous tumor cells that can be genetically manipulated and afterward implanted into humanized mice that have been reconstituted with CD34+ HPCs from the same donor." (PMID 33013936, 2020). "Also expressed in primary tumor were CD34 (the tumor was rich in blood vessels), and OPN, confirming the isolated cells express the same marker genes as the primary tumor." (PMID 32652895, 2020). "Nevertheless, cardio-selective beta-blockers may affect partially tumor progression modulating tumor angiogenesis and CD34+ stromal fibroblast density." (PMID 32353988, 2020). "Of interest, neither CD34+ CAFs nor SMA+ CAFs were associated with the primary tumor size, localization and depth of infiltration (pT stage)." (PMID 31760702, 2020). "Furthermore, previous related studies have also shown that CD34+ skin CSCs reside near the tumor vasculature at the tumor stromal interface and express Vegfa." (PMID 31959281, 2020). "In addition to confirming the presence of a high population of TCs/CD34+SCs in these tumours, we suggest that these cells can be a source of the myxoid component present in some of them." (PMID 33353193, 2020). "However, sphere formation assays revealed that knockdown of CD34 significantly reduced sphere formation in PKAP+ tumor cells." (PMID 32586050, 2020). "However, for ILC, we reported the exceptional finding that CD34+ fibroblasts are partially preserved in the tumor stroma." (PMID 32435886, 2020). "In conclusion, the facts support the hypotheses that CD34+SCs/TCs participate in the origin of myofibroblasts during repair and tumor stroma formation, and that there is a heterogeneous population of resident CD34+SCs/TCs with different roles." (PMID 33072740, 2020). "Moreover, EGFRover occurred more frequently in the tumours with a higher number of intratumoural lymphatic vessels and blood vessels assessed using podoplanin and CD34 staining, respectively (n = 472, Chi2 = 11.541, p = 0.009)." (PMID 32901137, 2020).
tumor (continued). "BRAF V600E mutations were linked to GG with CD34 expression, FGFR1 mutations to DNT, MYB alterations to AG and also IDG and PRKCA fusions to PGNT, suggesting the possibility to also develop a genetically driven tumor classification scheme for LEAT." (PMID 32151273, 2020). "The expression of MMP‐2 in our primary tumor cells could be related to the highly vascular nature of the UPS demonstrated by CD34 staining of primary tumor." (PMID 32652895, 2020). "Moreover, stromal CD34+ CAF count was significantly associated with PFS and OS independently of age, sex, TNM‐stage, histology, or tumor grading in stage I–III NSCLC patients." (PMID 31760702, 2020). "The tumor was histologically characterized by an infiltrative proliferation of spindle and round cells in a background of numerous small vascular channels as highlighted by CD34 staining." (PMID 32652895, 2020). "In addition, CD34 positive cells transplantation into immunocompromised mice generated secondary tumour after 31 days, whereas repeated transplantations into immunocompromised mice generated tumours in all animals after 16 days." (PMID 33123267, 2020). "CD34 staining by immunohistochemistry was used to observe the neovascularization in the tumor." (PMID 31061456, 2019). "The effectiveness of non-CTCs demarcation can be strengthened by combining targeting of CD45 with other biomarkers, like those specific for myeloid cells (CD11b), tumor-associated macrophages (CD68), erythrocytes (CD235a), endothelial cells (CD146), and hematopoietic stem cells (CD34)." (PMID 31185699, 2019). "In the present study, we first aimed to clarify which type of cells could be positive with CXCR4 in OSCC and whereby focused on CXCR4/CD34 double-positive tumor vasculatures in clinical specimens of OSCC." (PMID 31336612, 2019). "CD31, CD34, FKI-1, and von Willebrand factor are the most commonly used markers; however, mutation and poor differentiation of tumor cells may cause misdiagnosis, so comprehensive consideration of all these diagnostic approaches is important." (PMID 31804339, 2019). "CD34 positivity in preexisting blood vessels within the tumour stroma but negativity or very scarce CD105 expression indicates that ACC may use another source of nutrients to sustain its growth, as supported by previous studies." (PMID 30736793, 2019). "It has been confirmed in mouse implanted with human HCC that inhibition of STAT3 activation by antisense oligonucleic acid not only reduces the expression of VEGF and MMP-2 but also reduces the microvascular density (MVD) of CD34 positive in tumor tissues, inhibiting tumor metastasis to the liver." (PMID 31885639, 2019). "Interestingly, the aggressive tumor cells generating VM were found to express CD31 or CD34, probably because genetically deregulated tumor cells express angiogenic and vasculogenic markers." (PMID 30833656, 2019). "In addition, we measured angiogenesis-related biomarkers and found that miR-632-mimic upregulated MMP9 and CD34 expression in tumour tissues." (PMID 30612555, 2019). "The significant modulation of tumor microenvironment characterized by the loss of SMA(+) CAFs and increased CD34(+) vasculature in PD901 treated CCA may profoundly affect oxygen supplies to the tumor cells." (PMID 30741922, 2019). "MVD may be involved in the capacity of tumor tissue to induce angiogenesis, and CD34 is considered to be a sensitive and well-defined marker of hepatic microvessels." (PMID 31885639, 2019). "The tumor cells were also found to be non-reactive to the following; epitelialmembrane antigen (EMA), Leucocyte Common Antigen (LCA), anti-alpha Smooth MuscleActin (SMA), S-100, CD34, C-kit and Myo-D1 which confirmed the classification asundifferentiated tumor sites." (PMID 30892391, 2019).
tumor (continued). "Similarly, we observed a moderate correlation (R = 0.67, P = 0.03) between macrophage (CD68+) populations and a strong correlation (R = 0.92, P < 0.001) between cells positive for vessel marker CD34 when comparing the larger tumor specimen and core biopsy." (PMID 31772388, 2019). "IHC for CD34-positive microvessels expression was performed on tumor tissue." (PMID 31885639, 2019). "IHC was used to evaluate VEGFA, CD34 and proliferation marker Ki67 in tumor tissues." (PMID 30755242, 2019). "Moreover, the vascularity and tumor proliferation, as evaluated by CD34 (p = 0.0021) and KI-67 (p = 0.0451) staining, respectively, were higher in the CCL2-Vehicle group than in the Mock-Vehicle group." (PMID 31366997, 2019). "Immunohistochemically, the cluster of differentiation 34 (CD34) is a positive marker for mesenchymal tumor cells such as are found in SFTs, epithelioid sarcomas, and gastrointestinal stromal tumors (GISTs), exhibiting undesirable imperfections in sensitivity and specificity." (PMID 31020464, 2019). "However the strong correlation persisted in both central and peripheral tumor biopsies (central cores, R = 0.80, P = 0.005; peripheral cores R = 0.98, P = 0.01) for CD34-positive cells." (PMID 31772388, 2019). "The increase in CD34+ and VWF+ cells in DTs and RTs caused by the infiltration of circulating cells might increase vessel diameter, which is crucial for tumor recurrence after radiation." (PMID 31803626, 2019). "This counterintuitive observation suggests that assessments of MVD as performed on TMA by IHC using anti-CD34 or anti-CD105 antibodies considered to be specific for endothelial cell markers might underestimate the extent of the tumor vascularity in HNSCC." (PMID 29748768, 2018). "Furthermore, in the tumor, the Cd34 expression was significantly up-regulated compared to both TG non-tumoral (p < 0.01 at 12 months and p < 0.05 at ≥15 months) and WT groups (p < 0.001)." (PMID 30177788, 2018). "Pathologically, the tumor was located in the muscularis of the prostatic urethra and consisted of spindle cells with fascicular and storiform patterns of growth, and exhibited strong diffuse expression of CD34." (PMID 30931143, 2018). "Immunohistochemical studies revealed that the tumor cells were positive for c-kit and CD34." (PMID 30472631, 2018). "In CD34+ hHSC-reconstituted, tumor-bearing models, treatment with LY3300054 resulted in an increase of the absolute number of human T cells, an enhanced CD8/CD4 T cell ratio, and increased frequency of PD1+ CD8+ and CD4+ T cells, indicative of T cell activation." (PMID 29712568, 2018). "Some studies have suggested that CD34+ stromal cells exhibit mesenchymal stem cell properties and are recruited from the microvasculature to contribute to the formation of reactive stroma in tumours like PCa31." (PMID 30254333, 2018). "Besides, USP4 expression was positively correlated with the expression of Ki67 (Tumor proliferation marker) and CD34 (microvessel marker)." (PMID 30335615, 2018). "The clinicopathological factors of 24 cases of PASTs such as age, sex, tumor size, histological type, mitotic index, CD117 expression, CD34 expression, DOG-1 expression, ulceration, and NIH risk classification were compared with 254 cases of GISTs from our center." (PMID 30445975, 2018). "Immunohistochemically, tumor cells were stained by vimentin and CD34." (PMID 30473900, 2018). "CD34 and Bcl-2 expression rates were lower in higher grade tumours." (PMID 30183767, 2018). "Analysis of CD34 expression conducted using Student’s t test demonstrated significantly higher mean MVD/CD34 values in the tumor region (21.04 ± 6.47) compared to the normal control group (9.91 ± 1.67), (t = 5.87 for p = 0.001) and the dysplasia group (16.27 ± 3.25), (t = 2.36 for p = 0.02)." (PMID 29748768, 2018).
tumor (continued). "To exclude the possibility that the observed differential expression of FTL was caused by differences in microvessel densities between SQCLC and HNSCC, we performed CD34 staining, which confirmed similar microvessel densities in the two tumour types (Fig EV2C)." (PMID 30097507, 2018). "One possible solution to this problem could be the production of a humanized xenograft model in which the CD34+ cells and implemented tumor tissue are derived from the same donor." (PMID 30079312, 2018). "Also, IL‐37‐over‐expressing tumors had decreased CD34 level, which suggested an inhibited tumor angiogenesis." (PMID 30004182, 2018). "In contrast, Notch1 immunolabeling could be easily observed in cells surrounding the tumor nodules, similar to that of CD34, which marks endothelial cells (ECs)." (PMID 29545603, 2018). "CD34 is a frequently used marker for quantification of microvessel density in tumour tissue." (PMID 30602942, 2018). "Previously we showed that adult Tcl1-/- mice developed skin defects due to dramatic reduction of CD34 stem cell marker and proliferating TA cells in the hair follicle, as well as dysregulated proliferation/differentiation/apoptosis program in the interfollicular epidermis." (PMID 30286151, 2018). "Microvessel density (MVD) was assessed for tumor angiogenesis analysis using the CD34 antibody." (PMID 29760719, 2018). "Hence, these data together indicated a correlation between the expression of ETV2 and CD31+/CD34+ EC-like cells in the GBM tumor." (PMID 29527330, 2018). "We hypothesized that tumors arising at the anorectal transition zone in the Tgfbr2 cKO mice would contain a population of CD34-expressing cells, and that these cells would represent a population of tumor-propagating cells or so-called cancer stem cells (CSCs)." (PMID 28219480, 2017). "First, ALK expression was significantly higher in tumor cells in hypervascular lesions as compared to those adjacent to necrotic foci in GBMs, and was positively correlated to the microvascular density as determined by CD34 expression." (PMID 28837676, 2017). "In addition, the amount of microvessel density (MVD) determined using anti-CD34 mAb immunostaining in the the transplanted tumor tissues of TNBC cells." (PMID 29228721, 2017). "Neoangiogenesis occurred at the site of tumour engraftment as deduced from the CD34 staining." (PMID 28472196, 2017). "Because CD10 and CD34 are expressed by peritumoral stromal cells as well as tumor cells, we examined whether GREM1 has any associations with expression of stromal CD10 and CD34, and found a strong correlation of GREM1 expression with CD10 expression." (PMID 28346486, 2017). "Histopathological examination revealed aggressive angiomyxoma with estrogen receptors positivity in 75% of the tumor cells, progesterone receptors in 80% of the tumor cells, actin and CD34 positivity in blood vessels, desmin positivity, and Ki67 positivity in 3% of the cells." (PMID 28944124, 2017). "LRG1 and CD34 were tested in tumor tissues by immunohistochemistry (IHC)." (PMID 29029535, 2017). "Specific staining of capillary-like vessels by anti-CD34 was shown in tumor tissues." (PMID 28969036, 2017). "Orthotopic transplantation of rescued CD34+ SCC cells resulted in a two-fold delay in tumor latency compared to Tgfbr2 cKO CD34+ SCC cells infected with the empty vector, although all mice eventually developed tumors due to the inefficient infection rate of the rescue vector." (PMID 28219480, 2017). "Immunofluorescence staining revealed that all YFP+SCC cells located at the tumor–stroma interface expressed high levels of the hemidesmosomal α6 integrin and the focal adhesion marker β1 integrin, and a fraction of these expressed CD34." (PMID 28219480, 2017).